LIMK2 (LIM domain kinase 2)
Diseases named in the same sentence as LIMK2 in open-access papers (continued):
Sharing a sentence is not in itself a finding about the gene and the disease.
tumor (continued). "This idea is further supported by our mouse experiments, in which the treatment of MDA-MD-231 xenografts with the LIMK2 inhibitor LX7101 did not suppress primary tumor growth but did inhibit metastatic progression." (PMID 32859889, 2020). "We found that the LIMK2 inhibitor LX7101 blocked metastatic progression without significantly affecting primary tumor growth, indicating that LIMK2 is important in the distal metastatic progression of TNBC cells." (PMID 32859889, 2020). "Based on our results, we predict that LIMK2 promotes metastasis, but not tumor growth because the primary effect of LIMK2 is on phenotypes related to metastasis, such as invasion and migration." (PMID 32859889, 2020). "Importantly, RLH activation suppressed all of these responses and increased LIMK2, p-cofilin and the PTEN tumor suppressor gene while decreasing the expression of BRAF." (PMID 27198666, 2016). "In addition, the LIMK2 inhibitor T56-LIMKi inhibited the growth of subcutaneous tumor models of PAAD in mice by specifically inhibiting LIMK2 without cross-reacting with LIMK1." (PMID 37894409, 2023). "Moreover, the pharmacological inhibition of LIMK2 blocked metastatic progression in mice without affecting primary tumor growth." (PMID 32859889, 2020). "Such opposite findings suggest that targets of LIMK1 and LIMK2, which include ADF as well as cofilin, bring about different effects, which could be dependent on relative amounts of ADF or cofilin that are expressed in the different tumor cell types." (PMID 24093776, 2013). "Finally, this central role of LIMK2 in the migration of leading keratinocytes can be related to a previous work showing that, during cell invasion in vitro, LIMKs are required for path generation by leading the tumor cells and nontumor stromal cells during collective tumor cell invasion." (PMID 35159213, 2022).
cancer (20 papers, 2008 to 2025). A tumor composed of atypical neoplastic, often pleomorphic cells that invade other tissues. "Meanwhile, miRNA-939-5p has been demonstrated to be a valuable diagnostic and prognostic indicator in cancer by regulating LIMK2 expression." (PMID 40016789, 2025). "Researchers have also linked abnormalities in the ROCK1/LIMK2/cofilin pathway to various types of cancer." (PMID 39596356, 2024). "LIMK2 overexpression was also associated with increased cancer incidence and metastasis." (PMID 34678587, 2022). "LIMK2 was previously implicated in promoting metastatic behavior in various cancer models." (PMID 32859889, 2020). "LIMK2 inhibition or ablation can be considered as an alternative approach to modulating AURKA deregulation in cancer." (PMID 39334449, 2024). "Recent studies show that targeting LIMK2 in cancer and neurological disorders is promising, as LIMK2 inhibitors have shown efficacy in preclinical models." (PMID 39596356, 2024). "The expression level of LIMK2 was positively correlated with the overall survival of some cancers, contrary to previous studies." (PMID 35273591, 2022). "Previous research found that LIM domain kinase 2 (LIMK2) expression correlated with a poor prognosis in many cancers." (PMID 35273591, 2022). "Then, we further verified the expression level of LIMK2 in various cancers based on the StarBASE database." (PMID 35273591, 2022). "Based on these results, it can be stated that further research is required to analyze different aspects of LIMK1 and LIMK2 in various types of cancer." (PMID 34843456, 2021). "LIMK contains two distinct protein kinases (LIMK1, LIMK2) and both of them had been verified to be involved in cancer progression and metastasis." (PMID 32205841, 2020). "The two novel LIMK inhibitors described in the present study, CRT0105446 and CRT0105950, are potent inhibitors of LIMK1 and LIMK2 that will enable further development of LIMK-targeted cancer therapy." (PMID 26540348, 2015). "Several reports have shown that modulating LIMK1 expression by antisense, by overexpression of LIMK1 by a dominant negative form, or by knockdown of LIMK2 by ribozyme-mediated knockdown will inhibit cancer motility, invasion, and metastasis." (PMID 25237832, 2014). "Our results highlight the exciting possibility of combining specific LIMK2 inhibitors with anticancer drugs in the treatment of multi-drug resistant cancers." (PMID 23991158, 2013). "Similar to fascin-1, LIMK1 and LIMK2 contribute functionally to cancer cell invasion and metastasis, and are therefore of interest as therapeutic targets." (PMID 22883572, 2012). "In contrast our FRET studies identified a direct interaction between ROCK1 and LIMK2 in concentrated foci in the cytoplasm of cancer cells with a mesenchymal morphology." (PMID 18852895, 2008). "Since AURKA is overexpressed in various types of cancer, analysis of LIMK2 and AURKA levels could supplement standard staging information in primary biopsy samples." (PMID 39334449, 2024). "In this study, we first analyzed the expression level and prognostic value of LIMK2 across cancers." (PMID 35273591, 2022). "LIMK2 is also upregulated in multiple other cancers and promotes tumorigenesis and metastasis." (PMID 34066036, 2021). "LIMK2 is also expressed in other aggressive cancers; however, the molecular mechanisms leading to malignancy remain mostly unknown." (PMID 34066036, 2021). "That LIMK2 plays a prominent role in cancer is a fairly recent finding." (PMID 25593987, 2014).
cancer (continued). "However, there is little research on the role of LIMK2 in malignant tumors." (PMID 35273591, 2022). "Furthermore, LIMK2 may be a predictive marker of drug resistance as its elevated expression correlates with the resistance of human cancer cell lines to a wide range of chemotherapeutic drugs with different mechanisms of action." (PMID 23991158, 2013). "Using Aurora A-as7 kinase, we have identified several direct targets, including PHLDA1, LIMK2, ALDH1A1, SPOP, YBX1, and TWIST1, in cancer cells." (PMID 34066036, 2021). "We showed that LIMK2 stabilizes TWIST1 by direct phosphorylation at four sites, which leads to EMT and cancer stem cell phenotypes in CRPC." (PMID 34066036, 2021). "It has recently emerged that LIMK1 and LIMK2 also influence microtubule dynamics and have important functions in mitosis, which is consistent with LIMK inhibitors being potential cancer therapeutics." (PMID 26540348, 2015). "The reductions in metastases and in cancer cell-induced angiogenesis were similar for each of the LIMK1 and the LIMK2 single knockdowns." (PMID 25593987, 2014). "While we focused mostly on the use of a modified MYXV we were able to show that the effects of F11 on MYXV growth in cancer cells could be mimicked through the use of pharmacological inhibition or siRNA-mediated silencing of key regulators of cortical actin (RhoA, RhoC, mDia1, or LIMK2)." (PMID 24391902, 2013). "Both LIMK1 and LIMK2 belong to the LIMK family; despite their structural similarities, the LIMK1/LIMK2 may have different roles in cancer development and progression." (PMID 35273591, 2022).
infection (1 paper, 2025). The state of being infected such as from the introduction of a foreign agent such as serum, vaccine, antigenic substance or organism. "At 4 hours post infection (hpi), we noted high ROCK2 and LIMK2 activity, both cytoskeleton regulators, possibly reflecting changes that occur during viral entry." (PMID 40502089, 2025).
LIMK2 also shares sentences with these, for which no sentence is quoted: bipolar disorder (1 paper); breast invasive carcinoma (1); endothelial dysfunction (1); fibrosis (1); Hyperkeratosis (1); metastatic disease (1); neurodegenerative disease (1); neurodevelopmental disorder (1); neurological disorders (1); primary open-angle glaucoma (1); schwannoma (1); sterility (1); thyroid cancer (1).